STRA8 (stimulated by retinoic acid 8)
Description:
Meiosis-inducer required for the transition into meiosis for both female and male germ cells. In female germ cells, acts downstream of ZGLP1 as a key effector of the meiotic program: required for premeiotic DNA replication and subsequent events in meiotic prophase. During spermatogenesis, next to its role in meiotic initiation, promotes (but is not required for) spermatogonial differentiation. In complex with MEIOSIN, directly activates the transcription of a subset of critical meiotic genes playing a central role in cell-cycle switching from mitosis to meiosis.
Tractability: No criterion of Open Targets' tractability assessment is met for any kind of drug.
Gene: Protein-coding gene on chromosome 7 (135,231,979 to 135,258,663, forward strand). Ensembl gene ENSG00000146857.
Subcellular location: Cytoplasm; Nucleus
Subcellular location (Human Protein Atlas): Cytosol
Gene Ontology:
Molecular function: protein binding; protein dimerization activity
Biological process: activation of meiosis; cellular response to retinoic acid; meiotic cell cycle; oogenesis; regulation of transcription by RNA polymerase II; spermatogenesis
Cellular component: nucleus; cytoplasm
Genetic constraint (gnomAD): Loss-of-function variants: 14 observed, 29.1 expected, observed/expected ratio (o/e) 0.48, 90% interval 0.32 to 0.75. The upper end of that interval is the gene's LOEUF score, 0.75, which puts it in group 3 of 6, group 1 being the genes least tolerant of losing a copy. Missense variants: 317 observed, 357.45 expected, observed/expected ratio (o/e) 0.89, 90% interval 0.81 to 0.97. Synonymous variants: 149 observed, 142.76 expected, observed/expected ratio (o/e) 1.04, 90% interval 0.91 to 1.2.
Homologues: Orthologues: macaque STRA8 (91% identical), chimpanzee STRA8 (81% identical), dog STRA8 (78% identical), pig STRA8 (74% identical), rat Stra8 (68% identical), mouse Stra8 (67% identical), guinea pig STRA8 (66% identical), rabbit STRA8 (64% identical), tropical clawed frog stra8 (33% identical).
Diseases named in the same sentence as STRA8 in open-access papers:
STRA8 is named in the same sentence as 23 diseases in open-access papers, as found by Europe PMC text mining. Sharing a sentence is not in itself a finding about the gene and the disease. The quoted sentences say what the papers report.
Infertility (17 papers, 2012 to 2025). "To understand the cause of infertility in Stra8-Cre/Pdifl/fl male, we next examined the first wave of spermatogenesis at P10, P12, and P14 corresponding to leptotene, zygotene, and pachytene spermatocytes, respectively." (PMID 38912589, 2024). "Male germ cell-specific deletion of Srsf2 by Stra8-Cre caused complete infertility and defective spermatogenesis." (PMID 37867192, 2023). "We previously showed that deletion of Mgat1 in spermatogonia using Stra8-iCre prevents the formation of sperm, and thus causes infertility in male mice." (PMID 32300591, 2020). "The genetic variant and expression change of Stra8 showed higher risk of spermatogenic impairment in the groups of infertility, which implies Stra8 is critical in spermatogenesis." (PMID 25029539, 2014). "Eight single nucleotide polymorphisms (SNPs) in CYP26B1, NANOS1 and STRA8 genes were determined by TaqMan allelic discrimination assay in 719 idiopathic infertile men and 383 healthy controls." (PMID 23320086, 2013). "Together, these results account for the infertility phenotype observed in the Stra8-cre; Foxj2tg/tg males." (PMID 35908066, 2022). "We have previously shown that conditional deletion of Mgat1 in spermatogonia using Stra8-iCre (Mgat1 cKO) leads to a block in spermatogenesis and infertility." (PMID 32300591, 2020). "All adult Stra8-KO males were infertile and exhibited a significant reduction (~60%) in testis weight compared to WT controls." (PMID 27149259, 2016). "The genotype frequencies of rs10269148 in STRA8 were significantly different existed between the infertility/abnormospermia group and the control group." (PMID 23320086, 2013). "The depletion of Dcaf2 with Stra8‐Cre did not affect ovulation in female mice but caused infertility (data not shown), consistent with the results in which Dcaf2 was depleted with Gdf9‐Cre." (PMID 38837535, 2024). "Here, by crossing Srsf2Floxed/Floxed (Srsf2F/F) mice with Stra8-Cre mice to generate mutant mice with specific deletion of the Srsf2 gene in male germ cells, we found that the SRSF2 knockout caused complete infertility and germ cells were drastically lost during spermatogenesis." (PMID 37867192, 2023). "Interestingly, both FlipF/–;Stra8-Cre males and females are infertile." (PMID 37439366, 2023). "Therefore, by deleting Dicer1 from male germ cells, endo-siRNA levels may also be reduced and thus confound the etiology of the Stra8-icre;Dicer infertility phenotype." (PMID 23056286, 2012).
male infertility (8 papers, 2020 to 2024). The inability of the male to effect fertilization of an ovum after a specified period of unprotected intercourse. "The results of our previous study demonstrated that inactivation of Prmt5 in male germ cells using Stra8-Cre causes aberrant spermatogenesis and male infertility, suggesting that PRMT5 is essential for the development of male germ cells." (PMID 34113620, 2021). "The depletion of Dcaf2 in germ cells by crossing Dcaf2fl/fl mice with stimulated by retinoic acid gene 8(Stra8)‐Cre mice caused a reduction in progenitor spermatogonia and differentiating spermatogonia, eventually leading to the failure of meiosis initiation and male infertility." (PMID 38837535, 2024). "Both inducible whole-body PDI-KO (UBC-Cre/Pdifl/fl) mice and premeiotic PDI-KO (Stra8-Cre/Pdifl/fl) mice experienced a significant decrease in germ cells, testicular atrophy, oligospermia, and complete male infertility." (PMID 38912589, 2024). "Deletion of both TUT4 and TUT7 in pre-meiotic germ cells by using Stra8-Cre mice leads to spermatogenic arrest in the late pachytene stage, accompanied by cell apoptosis, ultimately resulting in spermatogenic failure and male infertility." (PMID 39310107, 2024). "These abnormally expressed genes, such as Stra8, Stag3, Atr and Dazl, caused by SRSF2 deletion finally result in the failure of spermatogenesis and male infertility." (PMID 37867192, 2023). "The results of our previous study revealed that the postnatal knockout of Prmt5 in male germ cells using Stra8-Cre led to defects in meiosis and male infertility." (PMID 34113620, 2021).
Azoospermia (5 papers, 2012 to 2021). Absence of any measurable level of sperm,whereby spermatozoa cannot be observed even after centrifugation of the semen pellet. "In the following stratified analysis, compared with homozygous type CC, the rs10269148 C>G increased the risk of azoospermia and displayed 2.92 fold increased risk of spermatogenic impairment, which was consistent with the phenotypes in STRA8−/− mice." (PMID 23320086, 2013). "Several genes that were downregulated in the KO testis are known to be involved in spermatogenesis, for example deleted in azoospermia-like (Dazl), stimulated by retinoic acid gene 8 (Stra8) and Piwi-like protein 1 (Piwil1)." (PMID 28706261, 2017). "Arguing against this possibility is the finding that both Stra8-icre;Dicerlox/lox and Stra8-icre;Droshalox/lox male mice are infertile with oligozoospermia or azoospermia due to constant depletion of pachytene spermatocytes and spermatids." (PMID 23056286, 2012).
embryonic carcinoma (3 papers, 2013 to 2019). "F9 cells are embryonic carcinoma cells that activate stimulated by retinoic acid gene 8 (Stra8) transcription in response to retinoic acid (RA) stimulation." (PMID 25986924, 2015). "Gene chip analysis in F9 embryonic carcinoma cells revealed that Stra8 can be positively regulated by either RA or TSA." (PMID 23785470, 2013). "Hence, to assess the role of STRA8 in autophagy suppression, STRA8 was ectopically and stably expressed in F9 embryonic carcinoma cells, a cell line regularly used for autophagy research." (PMID 31059511, 2019).
teratocarcinoma (3 papers, 2009 to 2019). A germ cell tumor characterized by the presence of an embryonal carcinoma component and a teratoma component. "Hence, STRA8 may have transcription regulatory activity given reports that STRA8 expression is found in the nucleus of primordial germ cells and teratocarcinoma cell lines." (PMID 31214493, 2019). "Stra8 is an important gene for induction of differentiation of mouse P19 teratocarcinoma cells by ATRA, and Stra8 plays an key role in the process of induction of meiosis and normal meiotic prophase." (PMID 26606052, 2015). "Furthermore, the susceptibility of three maGSC lines (maGSC Stra8 SSC5, maGSC 129/Sv, maGSC C57BL) to CTLs has been determined in comparison to corresponding ESC lines (ESC Stra8, ESC 129/Sv R1, ESC C57BL), iPSCs, and F9 teratocarcinoma cells." (PMID 19715575, 2009).
female infertility (2 papers, 2020 to 2022). Diminished or absent ability of a female to achieve conception. "While the knockout of Cxxc1 in male germ cells using transgenic Stra8-Cre did not affect spermatogenesis and male fertility, the deletion of Cxxc1 in a Stra8-Cre knockin mouse strain resulted in male and female infertility." (PMID 33163498, 2020).
Testicular atrophy (2 papers, 2020 to 2024). Wasting (atrophy) of the testicle (the male gonad) manifested by a decrease in size and potentially by a loss of fertility. "Of note, Trim28 deletion using the Stra8-Cre deleter strain yielded an initially unexpected milder testicular degeneration phenotype, which could be explained by the activation of Stra8-cre in response to retinoic acid in late undifferentiated spermatogonia, hence avoiding recombination in SSC." (PMID 32302554, 2020).
colorectal cancer (1 paper, 2014). A primary or metastatic malignant neoplasm that affects the colon or rectum. "To do this, we selected a small sub-group of these genes that remained transcriptionally silenced in the colorectal cancer cell lines HCT116 and SW480 (ARRDC5, C4orf17, C20orf201, DDX4, NT5C1B, STRA8, TDRD12)." (PMID 25594001, 2014).
cryptorchidism (1 paper, 2024). The failure of one or both testes of a male fetus to descend from the abdomen into the scrotum during the late part of pregnancy. "In addition, RA concentration and RA gene 8 (Stra8) expression are significantly lower in mice with cryptorchidism than in normal controls." (PMID 38994945, 2024). "Therefore, RA supplementation or up-regulation of Stra8 may offer new hope for the treatment of cryptorchid spermatogenesis." (PMID 38994945, 2024).
germ cell tumours (1 paper, 2021). "The importance of better understanding the c‐KIT and STRA8 regulation is not only related to spermatogenesis, but extend also to testicular germ cell tumours." (PMID 33236849, 2021).
metabolic syndrome (1 paper, 2023). A cluster of metabolic risk factors for CARDIOVASCULAR DISEASES and TYPE 2 DIABETES MELLITUS. "PIK3R2, STRA8, FLT1, DMRT1, FGF22, NR5A2, and FLT genes were up-regulated in metabolic syndrome after exercise." (PMID 37053002, 2023). "PIK3R2, STRA8, FLT1, DMRT1, FGF22, NR5A2, and FLT were up-regulated and PRDM14, POU5F1, and KDR were down-regulated in metabolic syndrome after exercise." (PMID 37053002, 2023).
ovarian disease (1 paper, 2023). "Although STRA8 and MEIOSIN are well known for their roles in initiating meiosis in animal models, our findings highlight their critical roles in human ovarian disease." (PMID 36732629, 2023).
Premature ovarian insufficiency (1 paper, 2018). Amenorrhea due to loss of ovarian function before the age of 40. "More importantly, two novel mutations of the WDR62 gene were detected in patients with premature ovarian insufficiency (POI), and these mutations played dominant-negative roles in regulating Stra8 expression." (PMID 30102701, 2018).
sterility (1 paper, 2022). "Five genes (Tsga10, Terb1, Stra8, Tex14, and Spam1) were predicted to be associated with sterility in male and female Mule ducks." (PMID 36386800, 2022).
testicular teratoma (1 paper, 2021). "STRA8 and the premature germ cell differentiation are associated to susceptibility to testicular teratomas." (PMID 33236849, 2021).
cancer (4 papers, 2012 to 2019). A tumor composed of atypical neoplastic, often pleomorphic cells that invade other tissues. "A number of meiosis-specific CT genes including, but not limited to SPO11, STRA8, DMC1, REC8, STAG3, SGO2, SYCP1/2/3 and HORMAD1 have been shown to be expressed in various solid and hematological cancers as well as in different cancer cell lines." (PMID 30701021, 2018).
tumor (4 papers, 2014 to 2021). "Expression levels of SETD8 and H4K20me1 in S phase of STRA8 overexpression GC1 cells were different from that previously observed in tumour cell lines." (PMID 32090428, 2020). "Intriguingly, STRA8 is located on human chr7, copies of which are lost in 10/14 of SpT cases, suggesting that the expansion of tumor cells may be driven by an altered balance of RA pathway effectors that converge to inhibit the mitosis-meiosis transition." (PMID 28542371, 2017). "Additionally, activation of STRA8 requires slightly higher concentrations of 5-aza-CdR in SW480 than HCT116, which indicates subtle regulatory differences between tumour cell types." (PMID 25594001, 2014).
STRA8 also shares sentences with these, for which no sentence is quoted: oligospermia (2 papers); vitamin A deficiency (2); Cirrhosis (1); cyst (1); neuroblastoma (1); teratoma (1).